SORT1 (sortilin 1)
Description:
Functions as a sorting receptor in the Golgi compartment and as a clearance receptor on the cell surface. Required for protein transport from the Golgi apparatus to the lysosomes by a pathway that is independent of the mannose-6-phosphate receptor (M6PR). Lysosomal proteins bind specifically to the receptor in the Golgi apparatus and the resulting receptor-ligand complex is transported to an acidic prelysosomal compartment where the low pH mediates the dissociation of the complex. The receptor is then recycled back to the Golgi for another round of trafficking through its binding to the retromer. Also required for protein transport from the Golgi apparatus to the endosomes. Promotes neuronal apoptosis by mediating endocytosis of the proapoptotic precursor forms of BDNF (proBDNF) and NGFB (proNGFB). Also acts as a receptor for neurotensin. May promote mineralization of the extracellular matrix during osteogenic differentiation by scavenging extracellular LPL. Probably required in adipocytes for the formation of specialized storage vesicles containing the glucose transporter SLC2A4/GLUT4 (GLUT4 storage vesicles, or GSVs). These vesicles provide a stable pool of SLC2A4 and confer increased responsiveness to insulin. May also mediate transport from the endoplasmic reticulum to the Golgi.
Synonyms: Gp95; NT3; NTR3; LDLCQ6
Tractability: Small molecule: a structure with a bound ligand is known; a high-quality ligand is known; it has a high-quality binding pocket. Antibody: UniProt places it where antibodies can reach, with high confidence; its Gene Ontology location is reachable by antibodies, with high confidence; UniProt predicts a signal peptide or a membrane-spanning region; the Human Protein Atlas places it where antibodies can reach. PROTAC: ubiquitination databases record sites on it; its protein half-life has been measured; a small molecule that binds it is known.
Target class: Membrane receptor
Gene: Protein-coding gene on chromosome 1 (109,309,568 to 109,397,967, reverse strand). Ensembl gene ENSG00000134243.
Subcellular location: Golgi apparatus, Golgi stack membrane; Endosome membrane; Endoplasmic reticulum membrane; Nucleus membrane; Cell membrane; Lysosome membrane
Subcellular location (Human Protein Atlas): Cytosol; Golgi apparatus; Plasma membrane
Pathways (Reactome):
Vesicle-mediated transport: Golgi Associated Vesicle Biogenesis
Gene Ontology:
Molecular function: cargo receptor activity; enzyme binding; nerve growth factor binding; protein binding; retromer complex binding; nerve growth factor receptor activity; neurotensin receptor activity, non-G protein-coupled
Biological process: endocytosis; endosome to lysosome transport; endosome transport via multivesicular body sorting pathway; Golgi to endosome transport; Golgi to lysosome transport; Golgi to plasma membrane transport; myotube differentiation; plasma membrane to endosome transport; response to insulin; vesicle organization; maintenance of synapse structure; nerve growth factor signaling pathway
Cellular component: cell surface; clathrin-coated pit; clathrin-coated vesicle; cytoplasmic vesicle; cytosol; early endosome; endosome membrane; Golgi apparatus; lysosome; perinuclear region of cytoplasm; plasma membrane; membrane; trans-Golgi network transport vesicle; cerebellar climbing fiber to Purkinje cell synapse; cytoplasmic vesicle membrane; endoplasmic reticulum membrane; Golgi cisterna membrane; lysosomal membrane; nuclear membrane
Genetic constraint (gnomAD): Loss-of-function variants: 16 observed, 43.91 expected, observed/expected ratio (o/e) 0.36, 90% interval 0.25 to 0.55. The upper end of that interval is the gene's LOEUF score, 0.55, which puts it in group 2 of 6, group 1 being the genes least tolerant of losing a copy. Missense variants: 431 observed, 535.1 expected, observed/expected ratio (o/e) 0.81, 90% interval 0.74 to 0.87. Synonymous variants: 195 observed, 205.71 expected, observed/expected ratio (o/e) 0.95, 90% interval 0.84 to 1.07.
Homologues: Orthologues: chimpanzee SORT1 (99% identical), macaque SORT1 (99% identical), pig SORT1 (94% identical), dog SORT1 (93% identical), mouse Sort1 (90% identical), rat Sort1 (90% identical), rabbit SORT1 (90% identical), guinea pig SORT1 (84% identical), zebrafish sort1a (61% identical), zebrafish sort1b (60% identical), tropical clawed frog sort1 (59% identical). Paralogues in human: SORL1 (29% identical), SORCS2 (24% identical), SORCS3 (23% identical), SORCS1 (22% identical).
Diseases named in the same sentence as SORT1 in open-access papers:
SORT1 is named in the same sentence as 118 diseases in open-access papers, as found by Europe PMC text mining. Sharing a sentence is not in itself a finding about the gene and the disease. The quoted sentences say what the papers report.
atherosclerosis (18 papers, 2014 to 2025). A disease characterized by the build-up of fatty material and calcium deposition in the arterial wall resulting in partial or complete occlusion of the arterial lumen. "The regulatory influence of miR‐146a on SORT1 has previously been implicated in other pathological conditions, including atherosclerosis and cerebral ischemia/reperfusion injury." (PMID 40781926, 2025). "Sortilin, encoded by the SORT1 gene, is implicated in the pathogenesis of atherosclerosis, primarily through its regulation of low-density lipoprotein cholesterol (LDL-C) and very low-density lipoproteins (VLDL)." (PMID 38913092, 2024). "Since high LDL-C is a cause of atherosclerosis, a common underlying cause of IS, genetic variation in SORT1 might indirectly influence stroke risk by lipid regulation." (PMID 40863347, 2025). "Aberrant SORT1 expression contributes to atherosclerosis by promoting lipoprotein imbalance, arterial inflammation, and vascular calcification." (PMID 40242450, 2025). "Research has shown that the SORT1 gene within the 1p13.3 locus is an important modulator of LDL-cholesterol level and atherosclerosis risk." (PMID 38913092, 2024). "The effects of SORT1 on lipid metabolism and development of atherosclerosis have been explored, particularly focusing on sortilin's effects in hepatocytes and macrophages." (PMID 38913092, 2024). "Human GWAS first revealed an unusually strong association between regulatory SNPs near the SORT1 locus, SORT1 expression, and LDL-C, a major risk factor for atherosclerosis." (PMID 35724703, 2022). "SORT1 augments PCSK9 secretion, and has been implicated in development of atherosclerosis." (PMID 37940228, 2023). "Recent studies have revealed a role for SORT1 in Apo-B secretion and LDL catabolism: overexpression of SORT1 resulted in increased serum LDL and loss-of-function mutations were associated with protection against hypercholesterolemia and atherosclerosis." (PMID 25528061, 2014). "Moreover, polymorphism of the genomic region-rs646776 within the cadherin endothelial growth factor (EGF) LAG seven-pass G-type receptor 2 (CELSR2), proline/serine-rich coiled-coil 1 (PSRC1), and sortilin 1 (SORT1) gene cluster is related to dyslipidemia and atherosclerosis." (PMID 36913212, 2023). "The study found that knockdown of Sort1 in rat intimal cells protects them from proNGF-induced apoptosis suggesting that sortilin represents an important regulator of proNGF-induced SMC apoptosis and arterial remodeling and through this action may contribute to the progression of atherosclerosis." (PMID 35724703, 2022).
coronary artery disease (15 papers, 2016 to 2025). "The relevance of sortilin in cardiovascular health is underscored by the genetic association of SORT1 gene variations with an increased risk of coronary artery disease." (PMID 38913092, 2024). "Genetic variants in the genomic region containing SORT1 (encoding the protein sortilin) are strongly associated with cholesterol levels and the risk of coronary artery disease (CAD)." (PMID 33937362, 2021). "Dysregulation of SORT1 is associated with coronary artery diseases." (PMID 37026480, 2023). "This has been supported by genome-wide association studies identifying a link between genetic variation at the human chromosomal locus 1p13.3, where the SORT1 gene is located, and coronary artery disease." (PMID 38913092, 2024). "Taken together, these results indicate that several SORT1 gene SNPs hold a genetic link between serum lipid hemostasis with the pathogenesis of cardiometabolic syndrome, including obesity, hypertension, and the atherosclerotic related coronary artery disease." (PMID 34784266, 2022).
Obesity (15 papers, 2015 to 2025). Accumulation of substantial excess body fat. "Obesity was significantly more often associated with AAA development for the genotype mutation of SORT1 rs599839[G] (p = 0.025, OR 2.419, 95% CI [1.101–5.314])." (PMID 37893562, 2023). "As obesity and metabolic dysfunction are cardiovascular risk factors, we assessed whether Sort1 deficiency altered adipose tissue in atherosclerotic mice." (PMID 29899496, 2018). "Studies on SORT1 knockout mice have shown that they exhibit resistance to obesity and increased insulin sensitivity." (PMID 38082425, 2023). "We also point out that the Sort1–/– mouse model used in these experiments was protected from diet-induced obesity, was more insulin sensitive, and had decreased hepatic steatosis, as shown in a report from an another group." (PMID 35113816, 2022). "On the other hand, the gene expression content of SORT1 has also been shown to be reduced under multiple pathological statuses, such as diabetes mellitus, hypertension, and obesity." (PMID 34784266, 2022). "The NTS-mediated glucose metabolism is likely mediated through SORT1 as evidenced by the fact that Nts KO and Sort1 KO mice show resistance to obesity and hepatic steatosis, and greater insulin sensitivity on a high fat diet as common phenotypes." (PMID 33384578, 2020). "Additionally, several proteins were linked to metabolic disorders such as obesity, diabetes, and hyperuricemia, including AGRP, LEP, SORT1 and SOD2." (PMID 40242450, 2025). "To summarize, according to the cooperative reaction of two pathways induced by activation of receptors SORT1 and OSBPL2, obesity can drive malignant obese PCa." (PMID 35164166, 2022). "Sort1 deficiency generated by deleting 41 codons in exon 14, resulting in a reading frame disruption, reduced body weight gain and visceral fat in diet-induced obesity male C57BL/6 mice; without altering viability, fertility, or showing any gross abnormalities." (PMID 29899496, 2018). "Only a very small number of above-threshold GWAS loci, including SORT1 for LDL cholesterol, the FTO/IRX3 locus for obesity, and the SCN5A/SCN10A locus for QRS duration, have been investigated in detail." (PMID 27162171, 2016). "Additionally, numerous identified mQTL-SNPs cover previously identified GWAS loci for obesity, lipid and diabetes related traits e.g. POMC, GIPR, GRB10, FADS2, SORT1 and APOA5." (PMID 27322064, 2016). "We show that lipid modulating genes are dynamically regulated during adipogenesis and that variants near SORT1 and APOE influence lipid levels independent of obesity in children." (PMID 26375028, 2015). "We could show for the first time in children that rs599839 (SORT1) and rs4420638 (APOE) are strongly associated with alterations in blood lipid levels independent of the presence and degree of obesity." (PMID 26375028, 2015). "In addition to the apparent and expected impact of BMI SDS, rs599839 (SORT1) and rs4420638 (APOE) have a high certainty of affecting LDL-C independent of the degree of obesity." (PMID 26375028, 2015).
myocardial infarction (11 papers, 2012 to 2023). Gross necrosis of the myocardium, as a result of interruption of the blood supply to the area, as in coronary thrombosis. "Sortilin 1 (SORT1) encoding the transmembrane type I receptor sortilin is a risk gene for hypercholesterolemia and myocardial infarction." (PMID 28439730, 2017). "To illustrate a specific example, we examined the pattern of cell specific eQTL SNP-CRE overlap at the SORT1 locus, a well characterized myocardial infarction risk locus." (PMID 23935528, 2013). "SORT1 has been identified as a gene associated with blood LDL cholesterol levels and myocardial infarction risk, and its role in lipid metabolism has been investigated." (PMID 37958806, 2023). "As an example, we showed that a validated myocardial infarction locus interacts with the distal SORT1 promoter in CMs even though this locus has been extensively characterized in the context of cholesterol metabolism in hepatocytes." (PMID 29988018, 2018). "Genome wide association studies have connected the 1p13 locus harboring the Sortilin encoding gene, SORT1 to plasma low-density lipoprotein (LDL) cholesterol, myocardial infarction, aortic aneurysm, and coronary artery calcification." (PMID 29899496, 2018). "Despite functioning in the liver, we identified multiple promoter interactions between SORT1 and the myocardial infarction GWAS locus in CMs, directly implicating SORT1 as the target gene and lending further support to experimental validation of this locus as a SORT1 enhancer." (PMID 29988018, 2018). "For example, one of the strongest associations for myocardial infarction lies in-between the CELSR2 and PSRC1 genes on chromosome 1p13, but a careful screen of genes whose expression was affected by the risk allele implicated the more distal SORT1 gene." (PMID 29988018, 2018). "Similarly, the minor allele of rs12740374 has been associated with myocardial infarction, aberrant plasma levels of low-density lipoprotein cholesterol (LDL-C), and enhanced expression of SORT1 gene in the liver." (PMID 28186491, 2017). "One well-established example is the SORT1 gene at the 1p13 cholesterol locus, to which SNPs map that affect low-density lipoprotein cholesterol (LDL-C) and the risk of myocardial infarction (MI) in humans." (PMID 22275870, 2012).
dyslipidemia (10 papers, 2009 to 2023). "For instance, the first research, which found the relationship between SORT1 gene SNPs and the risk of dyslipidemia, used data of approximately 9,000 patients and discovered that SNPs of 18 gene loci had relationship with alterations of serum lipid profiles." (PMID 34784266, 2022). "There is considerable evidence linking the significant variability at the SORT1 gene locus with the increased risk of dyslipidemia and its related cardio-metabolic syndrome." (PMID 34784266, 2022). "Besides, this result also suggests that SORT1 gene SNP modulates the risk of dyslipidemia potentially through, at least partly, regulating the gene expression content of C/EBP." (PMID 34784266, 2022). "Rs12740374 in CELSR2/PSRC1/SORT1 cluster was associated with two lipid traits: total cholesterol and dyslipidemia in our study, which is closely related with previously reported associations with LDL cholesterol and lipoprotein-associated phospholipase A2 activity and mass." (PMID 30704471, 2019). "Otherwise, it still remains to be further explored whether the alteration of SORT1 gene expression results in dyslipidemia and its related metabolic diseases." (PMID 34784266, 2022). "Under the condition of dyslipidemia, the exposure of macrophage to circulating LDL-C results in increased expression of SORT1 gene and sortilin protein within macrophage." (PMID 34784266, 2022). "Increased miR-378a-3p further inhibits expression of Sort1, which subsequently promotes hepatic secretion of VLDL and aggravates the development of dyslipidemia." (PMID 32226531, 2020). "Among these genes, four of them, SORT1, FADS1, FADS2 and GALNT2, are recently reported as candidate genes at highly replicated genetic loci contributing to polygenic dyslipidemia." (PMID 20019805, 2009).
diabetes (9 papers, 2012 to 2025). "Importantly, carriers of SORT1 variant with diabetes had larger decreases in plasma apoB, TG, and VLDL and LDL particle number as compared with people without diabetes with the same variants." (PMID 35113816, 2022). "Second, among 61 previously identified CAD variants in the general population, two—SORT1 and KCNE2—were significantly associated with CAD among individuals with diabetes." (PMID 30003307, 2018). "We also found that the LDL-reducing variant at the SORT1 locus has a significantly greater effect in people with diabetes compared with those without diabetes." (PMID 35113816, 2022). "Interestingly, a recent study reported that these SORT1 SNPs were more protective against cardiovascular disease risk in people with type 2 diabetes compared with those without type 2 diabetes mellitus." (PMID 35113816, 2022).
breast carcinoma (8 papers, 2017 to 2025). "Previous studies had shown that SORT1 was overexpressed in breast cancer cells and underexpressed in normal cells." (PMID 38139459, 2023). "Indeed, GRN encoded protein, Progranulin, was shown to bind to SORT1 encoded protein, Sortilin 1, based on co-immunoprecipitation experiments performed in various mice cell lines and in green monkey fibroblasts, and on co-expression experiments in human breast cancer cell lines." (PMID 35264221, 2022). "SORT1 expression has been well assessed in TN breast cancer cells using Western blot." (PMID 39519199, 2024). "Similarly, high expressions of SORT1 were assessed in TN breast cancer samples." (PMID 39519199, 2024). "Sortilin-1 (SORT1) may be a promising target for ADC as it is upregulated in breast cancer." (PMID 38139459, 2023). "Although 8D302-MMAE showed higher anti-tumor activity in vitro and in vivo, the better safety profile of 8D302-DXd may enable it to be a promising therapeutic agent for the treatment of patients with solid cancers, especially breast cancers with SORT1-high expression." (PMID 38139459, 2023). "The fact that the scavenger receptor SORT1 is overexpressed in various types of ovarian, endometrial, and other types of cancers, such as breast cancer, further suggests that exploiting this receptor’s internalization functions could be used in other clinical indications." (PMID 35454785, 2022). "In breast cancer, NTR1 and SORT1 appear overexpressed in human samples and in human cancer cells regardless of hormone-sensitive lines." (PMID 39519199, 2024). "Multiple novel PDC agents are currently in clinical development, including TH1902 (targeting SORT1-positive advanced solid tumors, phase I trial), ANG1005 (for breast cancer brain metastases, phase II trial), and BT8009 (targeting nectin-4, phase I/II clinical trials)." (PMID 41001098, 2025). "Indeed, 66% were positive for SORT1 regardless of ER and progesterone receptor (PR) expression or the different molecular subtypes of breast cancer (luminal A and B, HER2+, TN)." (PMID 39519199, 2024).